MANBAL (mannosidase beta like)
Synonyms: dJ1141E15.2
Tractability: Antibody: UniProt predicts a signal peptide or a membrane-spanning region.
Gene: Protein-coding gene on chromosome 20 (37,289,559 to 37,317,260, forward strand). Ensembl gene ENSG00000101363.
Subcellular location: Membrane
Subcellular location (Human Protein Atlas): Mitochondria; Nucleoplasm
Gene Ontology:
Molecular function: protein binding
Cellular component: membrane
Genetic constraint (gnomAD): Loss-of-function variants: 1 observed, 6.02 expected, observed/expected ratio (o/e) 0.17, 90% interval 0.058 to 0.79. That is too few expected variants to judge how well the gene tolerates losing a copy. Missense variants: 100 observed, 110.13 expected, observed/expected ratio (o/e) 0.91, 90% interval 0.77 to 1.07. Synonymous variants: 47 observed, 46.4 expected, observed/expected ratio (o/e) 1.01, 90% interval 0.8 to 1.29.
Homologues: Orthologues: chimpanzee MANBAL (99% identical), guinea pig MANBAL (93% identical), rat Manbal (93% identical), dog MANBAL (91% identical), mouse Manbal (88% identical), rabbit MANBAL (87% identical), zebrafish manbal (62% identical), tropical clawed frog manbal (56% identical), Drosophila melanogaster CG4101 (28% identical).
Diseases named in the same sentence as MANBAL in open-access papers:
MANBAL is named in the same sentence as 1 disease in open-access papers, as found by Europe PMC text mining. Sharing a sentence is not in itself a finding about the gene and the disease.
MANBAL shares sentences with these, for which no sentence is quoted: tumor (1 paper).